CYP4F8 (cytochrome P450 family 4 subfamily F member 8)
Description:
A cytochrome P450 monooxygenase involved in the metabolism of endogenous polyunsaturated fatty acids (PUFAs) and their oxygenated derivatives (oxylipins). Mechanistically, uses molecular oxygen inserting one oxygen atom into a substrate, and reducing the second into a water molecule, with two electrons provided by NADPH via cytochrome P450 reductase (CPR; NADPH-ferrihemoprotein reductase). Catalyzes the hydroxylation of carbon hydrogen bonds, with preference for omega-1 and omega-2 positions. Hydroxylates (5Z,8Z,11Z,14Z)-eicosatetraenoic acid (arachidonate) predominantly at omega-2 position to form (18R)- hydroxyeicosatetraenoic acid (18R-HETE). Exhibits omega-1 hydroxylase activity toward prostaglandin (PG) H1, PGH2 and PGI2. Catalyzes the epoxidation of double bonds of PUFAs, including docosahexaenoic and docosapentaenoic acids. Shows little activity against PGD2, PGE1, PGE2, PGF2alpha, and leukotriene B4.
Synonyms: CPF8; CYPIVF8
Tractability: Antibody: UniProt predicts a signal peptide or a membrane-spanning region. PROTAC: ubiquitination databases record sites on it; a small molecule that binds it is known.
Target class: Enzyme; Oxidoreductase
Gene: Protein-coding gene on chromosome 19 (15,615,218 to 15,630,639, forward strand). Ensembl gene ENSG00000186526.
Subcellular location: Endoplasmic reticulum membrane; Microsome membrane
Pathways (Reactome):
Metabolism: Eicosanoids; Fatty acids; Synthesis of Leukotrienes (LT) and Eoxins (EX)
Gene Ontology:
Molecular function: oxidoreductase activity, acting on paired donors, with incorporation or reduction of molecular oxygen, reduced flavin or flavoprotein as one donor, and incorporation of one atom of oxygen; alkane 1-monooxygenase activity; monooxygenase activity; heme binding; iron ion binding; oxidoreductase activity, acting on paired donors, with incorporation or reduction of molecular oxygen
Biological process: arachidonate metabolic process; icosanoid metabolic process; menaquinone catabolic process; phylloquinone catabolic process; prostaglandin metabolic process; fatty acid metabolic process
Cellular component: endoplasmic reticulum membrane
Genetic constraint (gnomAD): Loss-of-function variants: 58 observed, 58.57 expected, observed/expected ratio (o/e) 0.99, 90% interval 0.8 to 1.23. The upper end of that interval is the gene's LOEUF score, 1.23, which puts it in group 5 of 6, group 1 being the genes least tolerant of losing a copy. Missense variants: 680 observed, 708.61 expected, observed/expected ratio (o/e) 0.96, 90% interval 0.9 to 1.02. Synonymous variants: 288 observed, 280.93 expected, observed/expected ratio (o/e) 1.03, 90% interval 0.93 to 1.13.
Homologues: Orthologues: chimpanzee CYP4F8 (99% identical), rat Cyp4f39 (72% identical), mouse Cyp4f17 (71% identical), mouse Cyp4f13 (71% identical), mouse Cyp4f16 (71% identical), rat Cyp4f6 (71% identical), mouse Cyp4f37 (71% identical), rat Cyp4f37 (71% identical), guinea pig CYP4F8 (69% identical), rat Cyp4f37 (69% identical), Drosophila melanogaster Cyp4d2 (32% identical), Drosophila melanogaster Cyp4c3 (32% identical), and 26 more. Paralogues in human: CYP4F2 (81% identical), CYP4F11 (79% identical), CYP4F12 (78% identical), CYP4F3 (77% identical), CYP4F22 (60% identical), CYP4A11 (44% identical), CYP4A22 (43% identical), CYP4B1 (42% identical), CYP4X1 (38% identical), CYP4Z1 (37% identical), CYP4V2 (33% identical), CYP19A1 (21% identical).
Diseases named in the same sentence as CYP4F8 in open-access papers:
CYP4F8 is named in the same sentence as 14 diseases in open-access papers, as found by Europe PMC text mining. Sharing a sentence is not in itself a finding about the gene and the disease. The quoted sentences say what the papers report.
prostate carcinoma (5 papers, 2017 to 2024). A carcinoma that arises from epithelial cells of the prostate gland. "CYP4F8 can be identified as a novel therapeutic target in prostate cancer and is associated with the pharmacokinetics and toxicities of methotrexate, a fundamental drug for osteosarcoma." (PMID 36818393, 2023). "When stimulated, arachidonic acid is converted by CYP4F8 into various biologically active arachidonic acids, which induce the proliferation of prostate cancer cells." (PMID 36514150, 2022). "Over expression of CYP4F3 and CYP4F8 was reported in several studies to regulate tumour progression and proliferation in various types of cancers such as breast and prostate cancer." (PMID 33991433, 2021). "In prostate cancer, the genes PLA2G7, HPGD, EPHX2, and CYP4F8 exhibit significantly altered expression." (PMID 38172792, 2024). "We found one amplified gene in the in-frame fusion samples, hydroxyprostaglandin dehydrogenase 15-(NAD) (HPGD), which was reported as a therapeutic target in prostate cancer due to its involvement in the arachidonic acid pathway with PLA2G7, EPHX2, and CYP4F8." (PMID 29299133, 2017).
osteosarcoma (2 papers, 2020 to 2023). A usually aggressive malignant bone-forming mesenchymal neoplasm, predominantly affecting adolescents and young adults. "In conclusion, this study identified statistically significant associations for a genetic variant in SULT1E1 with MTX plasma levels and three genetic variants in CYP2B6 and CYP4F8 with thrombocyte counts after HD-MTX infusion in osteosarcoma patients." (PMID 32903464, 2020).
atopic dermatitis (1 paper, 2018). "Some of lipid metabolic genes discovered in our analysis were also reported as declined genes in patients with psoriatic (ACSBG1, ALOX15B, ELOVL3, FADS1, FADS2, and THRSP) or atopic dermatitis (CYP4F8, ELOVL3, FADS1, FADS2, FAR2, and HAO2)." (PMID 30021930, 2018).
breast carcinoma (1 paper, 2021). "Based on these findings, the upregulation of CYP4F3 and CYP4F8 in breast cancer can be confirmed along with their role in tumour progression as their overexpression was also identified in our study." (PMID 33991433, 2021).
diabetes (1 paper, 2016). "For example, in subjects with prediabetes versus controls, cytochrome P450, family 4, subfamily F, polypeptide 3 (CYP4F3), CYP4F8, Phospholipase A2, group IIC (PLA2G2C), and PLA2G4E were differentially methylated, while in subjects with diabetes versus prediabetes, CYP2E1 and PLA2G12A were involved." (PMID 27555869, 2016).
head and neck squamous cell carcinoma (1 paper, 2019). A squamous cell carcinoma that arises from any of the following anatomic sites: lip and oral cavity, nasal cavity, paranasal sinuses, pharynx, larynx, and salivary glands. "A similar pattern can be observed for CYP4F8, which is up-regulated in all cancers, except PRAD and head and neck squamous cell carcinoma (HNSC)." (PMID 31258835, 2019).
tumor (4 papers, 2017 to 2025). "While CYP4F8’s role in tumor progression is well established, its correlation with DR remains unclear." (PMID 39997761, 2025). "We report that the CYP genes with highest expression, ranked by the mean expression in tumor tissues for all patients, are: CYP1B1 (mean normalized expression 112.8), CYP4Z1 (92.2), CYP2A6 (75.7), CYP4X1 (65.1), CYP4B1 (31.5), CYP2A7 (30.8), and CYP4F8 (11.6)." (PMID 28684774, 2017). "Additionally, CYP4F8, PDZD3, CRTAC1, and LRTM1 were identified as potential tumor suppressor genes." (PMID 38172792, 2024).
CYP4F8 also shares sentences with these, for which no sentence is quoted: cancer (3 papers); age-related hearing loss (1); breast tumors (1); hearing loss (1); inflammation (1); prediabetes (1); steatosis (1).